FGF21 (fibroblast growth factor 21)
Diseases named in the same sentence as FGF21 in open-access papers (continued):
Sharing a sentence is not in itself a finding about the gene and the disease.
osteoarthritis (6 papers, 2021 to 2025). A noninflammatory degenerative joint disease occurring chiefly in older persons, characterized by degeneration of the articular cartilage, hypertrophy of bone at the margins and changes in the synovial membrane. "First, although we found that FGF21 had a positive effect on the progression of osteoarthritis, the chondrocytes isolated from the articular cartilage showed the particularity of differentiation." (PMID 34556628, 2021). "Given the potential therapeutic effect of FGF21, we hypothesized that FGF21 might reduce the progression of osteoarthritis, which was verified in the present study." (PMID 34556628, 2021). "Moreover, Fgf21, shown to alleviate senescence, apoptosis, and ECM degradation in osteoarthritis via the SIRT1‐mTOR signaling pathway, was upregulated in the agarose encased cells, together with Fgf1 and 2, markers of human fetal growth plate cartilage, and Fgfr3, a key regulator of chondrogenesis." (PMID 40415244, 2025). "However, as one of the degenerative diseases, no studies on the relationship between FGF21 and autophagy flux in osteoarthritis have been reported yet." (PMID 34556628, 2021).
overnutrition (6 papers, 2014 to 2024). An imbalanced nutritional status resulting from excessive intake of nutrients. "As seen from the other parameters in our study, water decreases fructose’s effect on metabolism and possibly prevents a stress response from overnutrition, which results in a decreased FGF21 response." (PMID 38750219, 2024). "Prolonged starvation, overnutrition, and glucagon all upregulated FGF21 expression, while insulin may inhibit FGF21 expression in the liver." (PMID 39296716, 2024). "In many of these studies, mRNA and protein expression of FGF21 have consistently been shown to be increased in WAT in the setting of overnutrition, raising the possibility that Ad-FGF21 could be a source of circulating FGF21 in this context." (PMID 35046901, 2021). "Similarly to GDF15, circulating FGF21 has also been shown to be largely derived from the liver in obese HFD fed mice raising the question of why two stress responsive hormones are secreted in this context of overnutrition." (PMID 36064109, 2022). "Thus, while overnutrition increases circulating FGF21 levels and adipose tissue FGF21 mRNA expression, it has not been conclusively demonstrated that circulating FGF21 derives from adipose tissue in that context." (PMID 35046901, 2021).
pneumonia (6 papers, 2013 to 2024). An acute, acute and chronic, or chronic inflammation focally or diffusely affecting the lung parenchyma, caused by an infection in one or both of the lungs (by bacteria, viruses, fungi, or mycoplasma.). "In another recent study elevated serum FGF21 concentration was an independent predictor of all-cause mortality, major adverse cardiovascular events, and pneumonia in hemodialysis patients." (PMID 39302236, 2024). "Our study revealed that serum higher FGF21 was an independent predictor of all-cause mortality, MACEs, and pneumonia in HD patients." (PMID 37724523, 2023). "The Kaplan-Meier curve showed that compared with the lower FGF21 group, the higher FGF21 group suffered a greater risk of pneumonia (39.0% vs. 25.0%, log-rank, p = 0.004)." (PMID 37724523, 2023). "The current research was the first prospective study to comprehensively analyze the relationship of circulating FGF21 levels with the incidence of MACEs, pneumonia, and all-cause mortality in HD patients from two centers." (PMID 37724523, 2023). "The optimal cutoffs for FGF21 to predict all-cause mortality, MACEs and pneumonia were 437.57 pg/mL, 216.99 pg/mL and 112.79 pg/mL." (PMID 37724523, 2023). "Our results revealed that the optimal cutoff value of FGF21 for predicting pneumonia was lower than that for predicting all-cause mortality in HD patients." (PMID 37724523, 2023). "Together with the published data, we hold the opinion that rising FGF21 concentrations may be a compensatory response to resist the progression of pneumonia in HD patients, which heralds an increased risk for pneumonia in these patients." (PMID 37724523, 2023). "Therefore, the aim of our study is to explore the relationship between FGF21 and MACEs, pneumonia and all-cause mortality in Chinese ESKD patients." (PMID 37724523, 2023). "Forth, the differences in the C index were 0.019, 0 and 0.006 respectively when FGF21 was included or excluded in the all-cause mortality, MACEs and pneumonia prediction models, which suggested that the inclusion of FGF21 had a small impact on the predictability of the models." (PMID 37724523, 2023). "We also established a nomogram based on FGF21 to predict the probability of 2, 3, and 4-year pneumonia-free survival in HD patients, with a c-index of 0.734 (95% CI, 0.690–0.778)." (PMID 37724523, 2023). "The survival nomogram, MACEs-free survival nomogram and pneumonia-free survival nomogram based on FGF21 constructed for individualized assessment of HD patients had a high C-index with 0.841, 0.706 and 0.734." (PMID 37724523, 2023). "In fact, in a previous study on patients with acute inflammatory response syndrome due to community-acquired pneumonia, FGF21 strongly correlated with the severity of pneumonia." (PMID 33846498, 2021). "FGF21 > 112.79 pg/mL was independently predictive of incident pneumonia in HD patients." (PMID 37724523, 2023). "However, after adjusting for other risk factors, the significantly independent correlation between FGF21 and pneumonia event only existed when FGF21 expressed as a categorical variable (HR, 1.784; 95% CI, 1.124–2.830; p = 0.014)." (PMID 37724523, 2023). "For this patient, the rise in FGF21 levels after a first descent could be attributed to an episode of nosocomial pneumonia developed during the ICU stay." (PMID 23999826, 2013). "However, up to date, whether FGF21 is correlated with MACEs and pneumonia and the impact of FGF21 on the all-cause mortality in patients with ESKD has not been fully yielded." (PMID 37724523, 2023). "ROC curve analyses showed that the optimal cutoff was 112.79 pg/mL for FGF21 to discriminate HD patients with pneumonia from those without, with a sensitivity of 78.5% and specificity of 34.4%." (PMID 37724523, 2023). "Notably, serum FGF21 levels were significantly higher in HD patients with pneumonia than those without." (PMID 37724523, 2023).
polycystic ovary syndrome (6 papers, 2015 to 2024). A disorder that manifests as multiple cysts on the ovaries. "In polycystic ovary syndrome and healthy subjects, a positive correlation was also found between FGF21 and LH and T (r = 0.43 p = 0.007; r = 0.38, P = 0.02, respectively)." (PMID 25850006, 2015).
preeclampsia (6 papers, 2015 to 2025). Preeclampsia is a hypertensive disorder of pregnancy that is characterized by new-onset hypertension with proteinuria presenting after 20 weeks of gestation, and depending on mild or severe forms may initially present with severe headache, visual disturbances, and hyperreflexia. "There have been limited studies on maternal FGF21 during pregnancy, with mixed findings on its relationship with preeclampsia, a risk factor for preterm birth." (PMID 36130475, 2022). "Additionally, these findings suggest that high levels of FGF-21 in the third trimester in women with mild preeclampsia, might contribute to protection against injury associated with high levels of NEFA and hypertensive disorders of pregnancy." (PMID 35883694, 2022). "Although the precise mechanisms responsible for driving preeclampsia remain to be elucidated, the role of FGF-21 in the pathophysiology of preeclampsia should be considered." (PMID 35883694, 2022). "This study investigated whether expression of placental FGF21, its receptors and co-receptor as well as its transcriptional regulators and metabolic targets differed in preeclampsia as compared to normal pregnancy." (PMID 25890271, 2015). "Gene expression levels of glucose transporters, which are targets of FGF21 signaling, were not affected by preeclampsia." (PMID 25890271, 2015). "All the studies discussed suggest that FGF-21, FGF-19 and FGF-23 may play an important role in fetal and neonatal growth and development, particularly in pregnancies complicated by metabolic disorders, such as GDM or gestational hypertension." (PMID 40648894, 2025). "To date, it is not clear whether placental FGF21 is differentially expressed in preeclampsia and if this could contribute to altered placental metabolism." (PMID 25890271, 2015).
bipolar disorder (5 papers, 2020 to 2023). A disorder of the brain that causes unusual shifts in mood, energy, activity levels and the ability to carry out day-to-day tasks. "In patients with bipolar affective disorder, FGF21 levels were significantly elevated after VPA treatment, and high FGF21 levels were significantly correlated with treatment outcome and the development of MetS." (PMID 37239168, 2023). "Another study on adult patients with depressed bipolar disorder received valproate treatment (500‐1000 mg daily) for 12 weeks showed a significant increase in FGF‐21 level from 167.7 to 207.1 pg/mL." (PMID 34379890, 2021). "We compared plasma FGF21 levels between 26 bipolar disorder patients and 51 healthy controls." (PMID 32267096, 2020).
brain injury (5 papers, 2019 to 2024). Acute and chronic (see also brain INJURIES, CHRONIC) injuries to the brain, including the cerebral hemispheres, CEREBELLUM, and brain STEM. "For example, it has been shown that FGF21 inhibits apoptosis by activating the PI3K/Akt signaling pathway to treat neonatal rats with hypoxic-ischemic brain injury." (PMID 34746149, 2021). "In addition to its potential as a biomarker for repetitive concussion and its potential cumulative effect on neurological pathology, FGF21 could be an effective therapeutic strategy for the guidance treatment of repetitive TBI." (PMID 32059364, 2020).
brain ischemia (5 papers, 2016 to 2025). Diminished or absent blood supply to the brain caused by obstruction (thrombosis or embolism) of an artery resulting in neurologic damage. "Compared with plasma FGF21, which peaks at 2 h poststroke in mice, cerebral FGF21 is largely induced at 7 d after brain ischemia in the cortical region around the lesion, and at 14 d in the striatum." (PMID 40021824, 2025). "A recent study showed that administration of lyophilized FGF21 protected cerebral ischemia in rats subjected with brain ischemia and neuron cell line." (PMID 30842736, 2019). "In the present study, TubA increased phosphorylation of ERK44/42 at Thr202/Tyr204, notably in the ischemic cortex, suggesting up-regulation of FGF-21 signaling after cerebral ischemia." (PMID 26790818, 2016). "Importantly, it is noted that lyophilized FGF21 protected cerebral ischemia in middle cerebral artery occlusion (MCAO) rats and neuronal cells via decreasing endoplasmic reticulum stress." (PMID 30842736, 2019). "Taken together, our findings suggest that FGF-21 may be neuroprotective against cerebral ischemia, and that TubA’s beneficial effects may be at least partially attributable to FGF-21 up-regulation." (PMID 26790818, 2016). "Because the role of FGF-21 in brain disorders is unknown, we examined change in FGF-21 expression in the brain after experimental cerebral ischemia and the effects of TubA on this regulation." (PMID 26790818, 2016). "Considering that factors upregulated in the acute period after brain ischemia commonly result in a detrimental outcome (such as IL-6, IL-15), we wondered whether increased cerebral FGF21 expression during the subacute and delay phases could play a positive role." (PMID 40021824, 2025). "There are three potential mechanisms by which TubA may up-regulate FGF-21 after cerebral ischemia." (PMID 26790818, 2016). "Our results demonstrated that LINC00894 regulated cerebral ischemia injury by stabilizing EIF5 and facilitating EIF5-ATF4-dependent induction of FGF21 and ACOD1." (PMID 39060766, 2024). "Effects of TubA on FGF-21 signaling, including up-regulation of β-Klotho and activation of ERK and Akt/GSK-3β after brain ischemia were consistent with its effects on FGF-21 mRNA and protein expression." (PMID 26790818, 2016). "Upon cerebral ischemia, rats increased their circulating levels of corticosterone, free fatty acids, and CRP, and decreased their plasma levels of FGF-21, while maintaining a constant level of FGF-15." (PMID 34073455, 2021).
chronic pancreatitis (5 papers, 2016 to 2024). A chronic inflammatory process causing damage and fibrosis of the pancreatic parenchyma. "Additionally, the loss of the FGF21 gene has been linked to increased intra-acinar triglyceride vacuole accumulation, and more severe edema and necrosis in chronic pancreatitis." (PMID 38304193, 2024). "Thus, FGF21 ameliorates pancreatic fibrosis in chronic pancreatitis by reducing M1- and M2-type macrophages in CP mice via the m-TOR signaling pathway." (PMID 39456138, 2024). "There is some evidence that FGF21 can be used as an anti-inflammatory in chronic pancreatitis." (PMID 36756310, 2023).
glioblastoma (5 papers, 2017 to 2025). The most malignant astrocytic tumor (WHO grade IV). "Collectively, these findings suggest that FGF21 expression is inversely associated with the risk of developing glioblastoma, whereas an increased risk is linked to elevated levels of CXCL9 and IL-33." (PMID 38784036, 2024). "Transcriptomic analysis showed that FGF21 expression was inversely associated with the risk of developing glioblastoma, whereas an increased risk was linked to elevated levels of CXCL9 and IL-33." (PMID 38784036, 2024). "Despite limited research on FGF21 in glioblastoma, we conducted enrichment analysis for genes associated with FGF21 using gene clustering tools to explore their potential biological mechanisms in glioblastoma." (PMID 38784036, 2024). "Altered tumor metabolism is a defining hallmark of glioblastoma; therefore, the regulation of abnormal cell metabolic states through FGF21 may reduce the risk of developing glioblastoma." (PMID 38784036, 2024). "Consequently, we conclude that elevated levels of circulating FGF21 are inversely correlated with the risk of developing glioblastoma." (PMID 38784036, 2024). "We found that in patients with glioblastoma, the expression of FGF21 in tumor tissues was reduced, and these patients had longer overall survival." (PMID 38784036, 2024). "The results demonstrated a significant downregulation of FGF21 expression in glioblastoma tissues, whereas both CXCL9 and IL-33 were notably upregulated." (PMID 38784036, 2024). "Pathway and functional enrichment analyses suggested that Cystatin D might exert its effects on glioblastoma through intracellular protein transport, whereas FGF21 might affect glioblastoma via glucose response mechanisms." (PMID 38784036, 2024). "Although the secretion of Cystatin D and FGF21 is not directly related to glioblastoma and its associated infiltrating immune cells, recent research has found that both the brain-liver axis and the brain-oral axis can have an impact on the central nervous system." (PMID 38784036, 2024). "However, despite similar associations observed in other analyses, no causal effects of Cystatin D and FGF21 on glioblastoma were identified (p > 0.05)." (PMID 38784036, 2024). "Therefore, Cystatin D and FGF21 may influence the occurrence of glioblastoma through the brain-oral or brain-liver axes." (PMID 38784036, 2024). "In addition, our transcriptomic analysis revealed the role of FGF21 in glioblastoma." (PMID 38784036, 2024). "To investigate the role of Cystatin D, FGF21, IL-33 and CXCL9 in glioblastoma, we analyzed the correlation between the expression of these genes and survival prognosis characteristics in patients with glioblastoma." (PMID 38784036, 2024). "It has been shown that inhibition of STAT3 in glioblastoma stem cells (GBM-SC) can promote the levels of histone H3K27 demethylation and the expression of neural-specific genes, such as FGF21, GDF15, and Myt1." (PMID 34217316, 2021). "In glioblastoma, FAP has been proven to promote tumor growth and invasion via hydrolysis of molecules such as brevican in the extracellular matrix and targeting downstream pathways and substrates, such as fibroblast growth factor 21 (FGF21)." (PMID 37316886, 2023). "Additionally, increased FGF21 expression positively correlated with improved overall survival (OS), whereas increased levels of CXCL9 and IL-33 were associated with decreased OS in patients with glioblastoma, although the difference was not statistically significant." (PMID 38784036, 2024). "Interestingly, although STAT3 inhibition induces neural genes, such as FGF21 and GDF15, neither Jmjd3 overexpression or STAT3 inhibition are sufficient to drive differentiation of the glioblastoma stem cells." (PMID 28384648, 2017).
liver cirrhosis (5 papers, 2014 to 2026). "In CHB patients who developed HBV-related liver cirrhosis, even lower serum FGF21 could be explained by worse liver function due to liver fibrosis." (PMID 29184085, 2017). "In our study, the abnormal elevation of serum FGF21 in HCC was more obvious, because the patients with CHB or liver cirrhosis had lower serum FGF21 levels." (PMID 29184085, 2017). "However, serum FGF21 levels were decreased in CHB patients, especially in patients with HBV-related liver cirrhosis, due to impaired hepatic protein synthesis capacity." (PMID 29184085, 2017).
lung carcinoma (5 papers, 2022 to 2026). "The role of FGF21 in lung cancer is poorly defined, however, recent reports suggest potential tumor‐promoting effect of FGF21, since it can accelerate cell growth and migration in a SIRT1/PI3K/AKT‐dependent way in vitro." (PMID 36642986, 2023). "FGF21 has also been shown to be upregulated in lung cancer tissue sample, both on the RNA and protein level." (PMID 36642986, 2023). "Furthermore, overexpression of FGF21 has been observed in various cancers including liver, thyroid, and lung cancer." (PMID 38238320, 2024). "Moreover, FGF21 expression was suppressed in TWIST2-overexpressed lung cancer cells, resulting in decreased cell viability, increased oxidative stress, and cell apoptosis." (PMID 36263162, 2022). "However, current research only focused on the autocrine function of FGF21 in lung cancers." (PMID 36263162, 2022). "In lung cancer, TWIST2 induces oxidative stress in cancer cells by regulating the FGF21-mediated AMPK/mTOR signaling pathway and prevents lung cancer from progressing." (PMID 36428665, 2022). "For example, exogenous FGF21 promotes thyroid cancer cell migration and invasion by upregulating FGFR-EMT signaling, while overexpressed FGF21 protects against oxidative stress in lung cancer through the Sirtuin 1/PI3K/AKT signaling pathway." (PMID 38238320, 2024).
papillary thyroid carcinoma (5 papers, 2019 to 2025). "FGF21 might be linked to other thyroid diseases as well, as higher FGF21 levels are associated with papillary thyroid cancer aggressiveness and might predict the development of Graves’ orbitopathy." (PMID 39452947, 2024). "Additionally, we analyzed the association between serum levels of FGF21 and diverse clinicopathologic parameters in patients with papillary thyroid carcinoma (PTC)." (PMID 31408968, 2019). "In papillary thyroid carcinoma, there was a positive correlation between FGF21 levels and histological grade, recurrence, and mortality." (PMID 39744501, 2025). "We are also aware of reports suggesting an important role of FGF21 in the progression of papillary thyroid carcinoma in obese patients." (PMID 32570721, 2020). "In addition, FGF21 contributes to the increased malignant potential of papillary thyroid carcinoma cells by activating the FGFR signalling pathway and enhancing epithelial-to-mesenchymal transition (EMT) signals." (PMID 40242310, 2025).